CD46 (CD46 molecule)
Diseases named in the same sentence as CD46 in open-access papers (continued):
Sharing a sentence is not in itself a finding about the gene and the disease.
asthma (7 papers, 2012 to 2025). "For example, miR-20a-5p, which is associated with CD46, is involved in autophagy-induced apoptosis and inflammation in asthma, but long-chain noncoding RNA can be used as “molecular sponge” of miR-20a-5p to participate in the regulation of target gene expression." (PMID 35619697, 2022). "CD46 directly associates with autophagy, induces autophagy, and reduces oxidative stress-mediated apoptosis of respiratory epithelial cells in patients with asthma." (PMID 35619697, 2022). "This suggests that CD46-inhibited oxidant-induced apoptosis may offer a new strategy to treat lung injuries linked to oxidative stress in asthma." (PMID 30154478, 2018). "This response is impaired in asthma: CD4+ T cells isolated from the PBMCs of patients with asthma have impaired production of IL-10 in response to CD3/CD46 stimulation compared with controls." (PMID 40309766, 2025). "Further studies are needed to clarify the effect of autophagy in asthma and the effect of modulating CD46 on lower airway inflammation." (PMID 30154478, 2018). "The mechanistic basis for failure to induce IL-10 production in the CD4+ T cells of individuals with asthma may be attributable to the favored expression of the cytoplasmic (cyt) tail isoform of CD46." (PMID 40309766, 2025). "However, due to the small number of participants, we were unable to assess CD46 expression on CD4+ T cells in patients with severe asthma (n = 3)." (PMID 39403120, 2024). "Our findings may provide further evidence regarding the practical application of CD46 in clinical practice to protect respiratory epithelium in patients with asthma." (PMID 30154478, 2018). "To evaluate the protective role of CD46-induced autophagy in the prevention of respiratory epithelium apoptosis in asthma, we evaluated hydrogen peroxide-induced epithelial cell death from CD46 mAb co-cultured with the autophagy inhibitor 3-methyladenine (3-MA)." (PMID 30154478, 2018). "This notably includes MS, asthma and RA, pathologies in which the CD46 pathway is defective." (PMID 23144765, 2012). "CD46 induced autophagy and decreased the oxidative stress-mediated apoptosis of respiratory epithelium, and this may offer a new therapeutic strategy to treat asthma." (PMID 30154478, 2018). "Our observations revealed significantly increased expression of CD46 on CD4+ T cells from AEA patients, with prominent elevation in mild and moderate asthma regardless of the allergy season." (PMID 39403120, 2024). "Additionally, we found that CD46 expression on CD4+ T cells was not dependent on serum 25-OH vitamin D levels in either HDs or AEA patients, even though AEA patients had decreased serum 25-OH vitamin D concentration, which was independent of asthma severity and division into CD46D/I groups." (PMID 39403120, 2024).
Autoimmunity (7 papers, 2008 to 2018). The occurrence of an immune reaction against the organism's own cells or tissues. "Thus, we also verified a significant decreased of CD95 that was associated with the CD46 down regulation, which has an important role in the down-regulation of immune responses; since severe autoimmunity is developed in human and mice with deficiency in the Fas pathway." (PMID 21573156, 2011). "CD46 is a co-stimulatory factor for the development of T-helper cells, and works through IL-10 release, suppressing immune responses to prevent autoimmunity." (PMID 30133498, 2018). "Further, cross-linking of MCP (CD46) with the TCR on naïve CD4+ T cells induces regulatory T cells, which are critical in the balance between autoimmunity and tolerance." (PMID 17878210, 2008). "Thus, lack of autocrine CD46 activation, such as in CD46-deficient patients, results in reduced Th1 responses and recurrent infections, whilst uncontrolled autocrine C3 activation and dysregulated CD46 engagement contributes to hyperactive Th1 responses in autoimmunity." (PMID 30405635, 2018). "Thus, lack of autocrine CD46 activation, such as in CD46- and C3-deficient patients, results in subnormal Th1 cell responses, whereas uncontrolled autocrine C3 activation and dysregulated CD46 engagement contribute to hyperactive Th1 cell responses in autoimmune pathologies." (PMID 26084023, 2015).
meningococcal disease (7 papers, 2007 to 2025). "Transgenic mice expressing human CD46 are susceptible to meningococcal disease because bacteria can cross the blood–brain barrier in these mice." (PMID 24107297, 2013). "Transgenic mice expressing the human complement regulator membrane protein, CD46, reported to bind the neisserial pilus, are more susceptible to disseminated meningococcal infection." (PMID 23935487, 2013). "We have shown that CD46 transgenic mice are susceptible to meningococcal infection." (PMID 21124975, 2010). "Further studies will address how CD46 influences the thyroid function and whether low constitutive T4 levels increases the susceptibility to meningococcal disease." (PMID 17311106, 2007). "Several non-CD46 expressing mice models have been evaluated to study the earlier stage of meningococcal infection by an intranasal infection route." (PMID 21124975, 2010). "In this study we showed the adult CD46 transgenic mice can also develop invasive meningococcal disease following intranasal infection." (PMID 21124975, 2010). "The human cell surface receptor CD46 transgenic mouse model (CD46+/+) has been demonstrated to mimic many aspects of meningococcal disease in humans." (PMID 21124975, 2010). "In this study, we used bioluminescent meningococci to image the disease progression in CD46 transgenic mice and demonstrated novel aspects of the dynamics of meningococcal disease." (PMID 17311106, 2007). "In conclusion, this study demonstrates that bioluminescent N. meningitidis strains together with the CD46 transgenic mouse model provide a potent tool for in vivo investigations of meningococcal disease." (PMID 17311106, 2007). "Therefore, CD46 transgenic mice represent a suitable model system to study meningococcal disease and test vaccines in vivo in adult mice." (PMID 17311106, 2007). "CD46 transgenic mice infected intraperitoneally (i.p.)with N. meningitidis are susceptible to meningococcal disease in contrast to nontransgenic mice that clear the infection and survive." (PMID 17311106, 2007). "Although the role of CD46 in Neisseria infection is still not absolutely clear, the model is working and is today to our knowledge the best available in vivo meningococcal infection model system." (PMID 21747953, 2011).
multiple sclerosis (7 papers, 2012 to 2024). A progressive autoimmune disorder affecting the central nervous system resulting in demyelination. "Secretion of IL-10 upon CD46 costimulation is largely impaired in T cells from patients with multiple sclerosis (MS)." (PMID 23144765, 2012). "A cross-talk of CD46 with vitamin D in T cells has previously been reported in multiple sclerosis and COVID-19 raising the question of whether similar link between CD46 and vitamin D in kidney disease could be present." (PMID 39200211, 2024). "However, looking into our phenotypic data we can verify that CTD (SLC22A5), Parkinson ́s disease (LRPPRC), multiple sclerosis (IL4R), 3-MCCD (MCCC1), and different cancer types (FANCE, MAD1L1 and CD46) have been reported by the participants." (PMID 36404349, 2023).
COVID-19 (6 papers, 2022 to 2024). A disease caused by infection with severe acute respiratory syndrome coronavirus 2. "The expression of genes regulated by CD46 was significantly higher in the lymphoid cells from the lungs of patients with more severe COVID-19." (PMID 35327350, 2022). "Moreover, CD46′s interaction with other SARS-CoV-2 structural proteins could potentially contribute to the pathogenesis of COVID-19 by exerting an immunosuppressive effect." (PMID 38140538, 2023). "Consequently, it is highly plausible that the interaction between SARS-CoV-2 and the human membrane cofactor protein CD46 could represent a yet-to-be-explored mechanism contributing to severe COVID-19 complications." (PMID 38140538, 2023). "The previous study has found higher CD46, CD55, and CD59 levels in monocytes of COVID-19 patients than in healthy people, especially CD55 levels correlated with plasma inflammatory markers such as CRP and serum amyloid A during acute infection." (PMID 36820087, 2023). "CD55 and CD59, but not CD46, are involved in the hyperactivation and deposition of the complement factors C3, C3b/iC3b/C3d and C5b-9 in infected lung lesions of coronavirus disease 2019 (COVID-19)-affected people." (PMID 39599800, 2024).
mesothelioma (6 papers, 2010 to 2023). A usually malignant and aggressive neoplasm of the mesothelium which is often associated with exposure to asbestos. "The MV-Edm receptor CD46 (cluster of differentiation 46) was demonstrated to be significantly higher in mesothelioma cells than in control cells." (PMID 28968974, 2017). "Among the surface markers known to be expressed by mesothelioma cell lines, our cell cultures were strongly positive for CD46, CD47, CD56 and CD63, while showed a variable positivity for CD140b and CD141." (PMID 20175889, 2010). "All mesothelioma cells lines (MSTO-211H, H226, and Mero-82) expressed high level of CD46 (93%, 99%, and 99%, respectively) and DSG2 (99%, 99%, and 98%, respectively) on their surfaces." (PMID 38053658, 2023). "Furthermore, results herein demonstrate that viral entry into mesothelioma cells is dependent upon the expression of CD46 and is independent of nectin-4." (PMID 28968974, 2017). "The correlation coefficient between CD46 and AdF35/GFP was also not significant, −0.20 (P = 0.80) in pancreatic carcinoma, 0.14 (P = 0.71) in esophageal carcinoma and 0.72 (P = 0.16) in mesothelioma." (PMID 28874135, 2017). "Our cell cultures were strongly positive for CD46, CD47, CD56 and CD63 and were also strongly positive for some markers never described before in mesothelioma cell lines, including CD55, CD90 and CD99." (PMID 20175889, 2010). "A recent study showed that CD46 expression was not downregulated on mesothelioma cells, and recombinant type 5 Ad which replaced the fiber-knob region with that of type 35 Ad, shifting the Ad receptors from CAR to CD46 molecules, dramatically improved the infectivity." (PMID 23484132, 2013).
pancreatic cancer (6 papers, 2012 to 2024). "Oncolytic adenovirus ‘GoraVir’ has strong lytic potential in both pancreatic cancer cells and cancer‐associated fibroblasts, which may be facilitated by its use of CD46 for viral entry." (PMID 38037840, 2024). "In conclusion, we have shown that GoraVir has strong lytic potential in pancreatic cancer cells and pancreatic CAFs and that this is facilitated by its use of CD46 for viral entry." (PMID 38037840, 2024). "The interaction analysis of CR1 with the HAdV5 L5 protein and CD46 with the HAdV3 L5 protein is also performed to compare the binding affinity of these receptors with pancreatic cancer receptors." (PMID 35359382, 2022). "Previous studies suggest that CD46, a membrane regulator of complement activation, is overexpressed on human malignancies including colorectal, cervical, and pancreatic carcinomas compared with their normal counterparts." (PMID 22266706, 2012). "The proteome analysis of pancreatic cancer cell lines detected CD46, while no clear correlation was observed between the cell line mRNA data for CD46 with the mass spectrometry (MS) data or fluorescence-activated cell sorting (FACS) data." (PMID 35359382, 2022).
thrombotic microangiopathy (6 papers, 2015 to 2025). The syndromes of microangiopathic hemolytic anemia, thrombocytopenia, and variable signs of organ impairment, due to platelet aggregation in the microcirculation. "Mutations in CD46 predispose to thrombotic microangiopathy with endothelial cell dysfunction." (PMID 25710174, 2015).
mastitis (5 papers, 2014 to 2025). Inflammation of breast tissue during lactation or postpartum due to an obstructed duct or infection. "One complement system variants in CD46 have been associated with mastitis susceptibility in dairy cattle, with functional evidence of alternative splicing affecting immune response." (PMID 41012793, 2025). "The mastitis-infected tissues revealed a relatively higher CD46-TV mRNA expression compared with healthy tissues (p < 0.05), indicating that the C allele would be associated with a reduced risk of mastitis." (PMID 25070150, 2014). "This suggests that there may be larger effect mutations on mastitis susceptibility than the mutation which produces the CD46-TV transcript." (PMID 25070150, 2014). "Similarly, the SNP of gene CD46 was also found to be associated with mastitis in bovines." (PMID 34222390, 2021). "Therefore, CD46-TV may play an important role in resistance to mastitis caused by Streptococcus." (PMID 25070150, 2014). "Similar findings were made regarding the SNP in the CD46 gene and mastitis in cows." (PMID 36669036, 2023).
adenovirus infection (4 papers, 2008 to 2019). "Together with our results with EnAd-CMV-GFP and EnAd-SA-GFP, we conclude that, though CD46 enables uptake of EnAd into murine cells, there are other factors at play that restrict the permissivity of murine cells to human adenovirus infection." (PMID 29898782, 2018). "Ocular adenovirus infection begins with attachment of its penton fiber knob to a primary receptor such as the coxsackie-adenovirus receptor, sialic acid, or CD46." (PMID 18221537, 2008).
colorectal cancer (4 papers, 1993 to 2018). A primary or metastatic malignant neoplasm that affects the colon or rectum. "This makes a strong case that colorectal cancers represent good targets for CD46-targeting species B adenovirus-mediated gene therapy." (PMID 27203670, 2016). "Since our finding from tumor microarray indicate that CD46 was overexpressed in cancers of the prostate and colon, fiber chimeric Ad5/35 vectors that have infection tropism for CD46 were employed to demonstrate its efficacy in colorectal cancers (CRC)." (PMID 27203670, 2016). "Our study demonstrated that CD46 is generally highly expressed in colorectal cancers, and based on this phenomenon, species B-based adenoviral gene therapy may be better suited than the currently used species C adenoviral vector like Ad5." (PMID 27203670, 2016). "Nevertheless, the majority of the tumor cell lines we studied showed increase in sensitivity to oncolytic MV infection when overexpressing CD46, thereby showing that lung and colorectal cancers, which are highly resistant to conventional treatments, are suitable targets for MV cancer virotherapy." (PMID 23586034, 2013). "Since CD46 was consistently expressed in colorectal carcinomas the low expression or even lack of CD59 in a subset of tumours might not lead to critical complement-mediated attack of CD59-negative tumour cells." (PMID 7692919, 1993).
glomerulonephritis (4 papers, 2011 to 2025). A renal disorder characterized by damage in the glomeruli. "Currently, more than 60 disease-associated CD46 mutations are known; most are linked to aHUS and other diseases, such as SLE, glomerulonephritis, and pregnancy-associated disorders." (PMID 40904461, 2025).
leukemia (4 papers, 2006 to 2026). A malignant (clonal) hematologic disorder, involving hematopoietic stem cells and characterized by the presence of primitive or atypical myeloid or lymphoid cells in the bone marrow and the blood. "Unlike control T cells, aPDL1-CART cells significantly halted the expansion and reduced the viability of co-cultured leukemia cells (Raji, CD46, and K562) overexpressing PD-L1, and this effect was paralleled by increased secretion of IL-2 and IFN-γ." (PMID 33653969, 2021). "On the other hand, several earlier investigations on hematological malignancies reported that CD46 expression was 2–8 folds higher in ALL, AML, CLL and CML patients and in leukemia cell lines compared to normal cells." (PMID 41526546, 2026). "The current study investigates the differential expression of membrane-bound complement regulatory proteins; CD46 and CD55 in leukemia." (PMID 41526546, 2026). "Flow cytometric analysis conducted for proteomic expression of CD46 and CD55 on cell surfaces of leukemia patients showed a reduction in expression by 1.2-fold and 2.8-fold in AML patients, respectively." (PMID 41526546, 2026). "Furthermore, the level of CD46 and CD55 gene expression was compared in male and female leukemia patients to investigate if gender difference affects their gene expression." (PMID 41526546, 2026).
meningitis (4 papers, 2006 to 2023). A disorder characterized by acute inflammation of the meninges of the brain and/or spinal cord. "One of the most oft used transgenic mouse is the human transgenic CD46 homozygous mouse (CD46+/+), which is susceptible to lethal sepsis and meningitis." (PMID 37375472, 2023). "The impact of the Nm surface structures required for binding to human cytokines on bacteraemia and meningitis progression was investigated in CD46 transgenic mice." (PMID 24107297, 2013). "Anti-CD46 staining showed a significant increase between normals compared to all meningitis case (Figure 3Ag/h)." (PMID 16948860, 2006). "Conversely, in meningitis, the ependyma, subependyma and choroid plexus epithelia were strongly stained for CD46 and CD35." (PMID 16948860, 2006). "Ependymal cells express CD55, CD59 and CD46 antigens in normal cases and the stainings were increased in meningitis cases." (PMID 16948860, 2006). "In this study, we assessed the capacity of brain epithelial cells to express membrane-bound complement regulators (ie, CD35, CD46, CD55 and CD59) in vitro and in situ by immunostaining of control and meningitis human brain tissue sections." (PMID 16948860, 2006). "CD46, a negative regulator of the classical and lectin pathways, aids in the dissemination of bacteria (N. meningitidis) and viruses [Measles virus and HHV-6] into the CNS, leading to meningitis and encephalitis, respectively." (PMID 34408631, 2021).
schizophrenia (4 papers, 2018 to 2024). A major psychotic disorder characterized by abnormalities in the perception or expression of reality. "In addition to CSPG4P11, which showed a significant SMR association with schizophrenia in the present study, these included CD46, encoding the CD46 complement regulatory protein, GOLGA2P7, encoding GOLGA2 pseudogene 2, and SLCO4C1, encoding Solute Carrier Organic Anion Transporter Family Member 4C1." (PMID 30419947, 2018). "For the CD46 locus, we found significant association corrected for multiple testing (false-discovery rate, FDR < 5%) for schizophrenia (in CD46 and CR1L) and for Alzheimer’s disease (in CR1)." (PMID 32843070, 2020). "In our literature survey, we found three genes in the isoform layer of models have schizophrenia-related reports (cytochrome P450 2D6 (CYP2D6), WNT5A, CD46)." (PMID 37738675, 2024).
acute leukemia (3 papers, 2020 to 2026). A clonal (malignant) hematopoietic disorder with an acute onset, affecting the bone marrow and the peripheral blood. "Our results showed a noticeable downregulation of CD46 mCRP in both acute leukemia types, ALL and AML compared to healthy controls where in AML samples CD46 expression was downregulated by 4 fold and in ALL it was downregulated by 5.5 fold compared to expression in healthy controls." (PMID 41526546, 2026). "In order to determine the effect of post transcriptional knockdown of CD46 and CD55 on cell viability in acute leukemia, MTT assay was performed where the absorbance of the formazan product was measured at 595 nm." (PMID 41526546, 2026). "This study highlights the role of complement regulatory proteins; CD46 and CD55 in the pathogenesis of acute leukemia through their contribution to immune evasion and their ability to exhibit protection of leukemic cells against complement-dependent cytotoxicity." (PMID 41526546, 2026).